RAG2 (recombination activating 2)
Diseases named in the same sentence as RAG2 in open-access papers (continued):
Sharing a sentence is not in itself a finding about the gene and the disease.
severe combined immunodeficiency (35 papers, 2009 to 2026). Severe combined immunodeficiency (SCID) comprises a group of rare monogenic primary immunodeficiency disorders characterized by a lack of functional peripheral T lymphocytes resulting in early-onset severe respiratory infections and failure to thrive. "Severe combined immunodeficiency (SCID) is causedby a large deletion on chromosome 11 spanning the RAG1and RAG2 genes and the 5′-region of TRAF6 (Weisz Hubshmanet al., 2017)." (PMID 37465191, 2023). "Mutations in the RAG2 Kelch domain block initiation of V(D)J recombination and lead to severe combined immunodeficiency (SCID) or Omenn syndrome (OS) immunodeficiency." (PMID 32139788, 2020). "A R229Q mutation of RAG2 was identified in patients with severe combined immunodeficiency (SCID) or Omenn syndrome (OS)." (PMID 30872621, 2019). "Genetic defects in RAG1 and RAG2 are known to impair V(D)J recombination, thereby causing T-B-NK+ severe combined immunodeficiency." (PMID 26186701, 2015). "Loss of function mutations in the recombination activating genes RAG1 and RAG2 have been reported to cause a T-B-NK+ type of severe combined immunodeficiency." (PMID 26186701, 2015). "However, unlike other IEI affecting B cell development resulting in agammaglobulinemia, variants in RAG1 or RAG2 cause severe combined immunodeficiency (SCID) because recombination of TCR chains during thymic development is also compromised." (PMID 37273190, 2023). "During V(D)J recombination, DNA double-strand breaks (DSBs) near the V, D, and J coding gene segments and recombination signal sequences are introduced by the recombination activating gene (RAG1 and RAG2) complex, and mutations in these two genes can lead to severe combined immunodeficiency (SCID)." (PMID 34825286, 2022). "Defects in RAG1 and RAG2 are known to cause a T-B-NK+ form of severe combined immunodeficiency." (PMID 26186701, 2015). "Omenn syndrome (OS) is a rare autosomal recessive form of severe combined immunodeficiency (SCID) caused by mutations in the RAG1 or RAG2 genes." (PMID 39802943, 2025). "In humans, mutations in RAG1 and RAG2 have been found in individuals with severe combined immunodeficiency (SCID), Omenn Syndrome, and combined immune deficiency with granulomas or autoimmunity (CID‐G/AI) (reviewed in 80)." (PMID 36939073, 2023). "Genetic defects in the recombination activating genes, RAG1 and RAG2 are known to impair V(D)J recombination in developing B and T-cells, thereby causing T-B-severe combined immunodeficiency (SCID)." (PMID 24678313, 2014). "Severe defects of V(D)J recombination, such as complete RAG1 or RAG2 deficiency, prevent proper rearrangement and recombination of the TCR and BCR genes and thus result in severe combined immunodeficiency (SCID), which impacts both T and B cell lineages." (PMID 41607487, 2025). "Mutations that inactivate RAG1 or RAG2 function in humans or knockout mice prevent antigen receptor rearrangement and block T and B lymphocyte development, leading to severe combined immunodeficiency (SCID)." (PMID 38467629, 2024). "Genetic defects that abrogate RAG1 or RAG2 function lead to the T- B- severe combined immunodeficiency (SCID), a life-threatening disorder of the adaptive immune system." (PMID 38022635, 2023). "The most extreme syndrome of lymphocyte dysfunction, severe combined immunodeficiency (SCID), arises from mutations in a number of genes: IL2RG, RAG1, RAG2, ADA, JAK3, and IL7RG." (PMID 36839582, 2023). "Nonsense mutations inRAG1/RAG2 completely annul this process and abrogate T- and B-lymphocyte receptor formation, leading to the most profound immunodeficiency syndrome, severe combined immunodeficiency (SCID)." (PMID 30800289, 2019). "Because of the profoundly depleted baseline T and B cell immunity in recombination activating gene 2 (RAG-2)-deficient severe combined immunodeficiency (SCID) patients, some of these factors are eliminated, and the immune recovery after BMT can then be clearly assessed." (PMID 22295088, 2012).
severe combined immunodeficiency (continued). "Inactivation of RAG1 or RAG2 leads to severe combined immunodeficiency (SCID)." (PMID 36311661, 2022). "Knockdown of RAG1 or RAG2 in mice results in lymphopenia and, therefore, severe combined immunodeficiency (SCID)." (PMID 35583713, 2022). "Genes commonly known to be associated with severe combined immunodeficiency (SCID), such as RAG1 and RAG2, are increasingly recognized among older adults with CID and autoimmunity." (PMID 35924244, 2022). "Severe combined immunodeficiency (SCID), caused by mutations in genes affecting lymphocyte development or function, such as IL-2RG, RAG1 and/or RAG2, and PRKDC, accounts for the most severe phenotypes among primary immunodeficient patients." (PMID 29593714, 2018). "This multiplexed HDR approach has been applied to model severe combined immunodeficiency (SCID) with biallelic knockouts of relevant genes and subsequently for gene correction of RAG2-SCID patient-derived CD34 + HSPCs by biallelic integration of a complete RAG2 cDNA." (PMID 37393268, 2023). "Immunocompromised mice, including athymic nude, severe combined immunodeficiency (SCID), Non-obese diabetic-SCID (NOD-SCID), and recombination-activating gene 2 (Rag2)-knockout animals, are used as hosts for human cell transplantation." (PMID 33809369, 2021).
breast carcinoma (24 papers, 2008 to 2024). "Previously we have shown that H. hepaticus-infected C57BL/6 ApcMin Rag2-deficient female mice develop mammary tumors with increased frequency." (PMID 25831236, 2015). "Intravenous injection of the exosomes on recombination-activating gene 2 (RAG2) knockout mice revealed the targeted delivery of let-7a miRNA to EGFR-expressing xenograft breast cancer tissues." (PMID 36839920, 2023). "In a study done using immunocompromised Rag2-/- mice which were humanized with fecal microbiota transplants from breast cancer patients, a genistein-supplemented diet increased the phylum Verrucomicrobia and the species Akkermansia muciniphila." (PMID 33440675, 2021). "To study the effect of 11PS04 on xenografts, we measured the tumors formed after subcutaneous injection of MDA-MB-436 human breast cancer cells into the right flank of Rag2−/− mice over 9 weeks." (PMID 31417117, 2019). "In agreement with our previous report, we observed mammary tumor development in a larger cohort of STAT1-/- × RAG2-/- female mice in similar disease incidences." (PMID 22264274, 2012). "In genetically engineered mice heterozygous for the Apc gene (ApcMin/+) and deficient in lymphocytes because of lack of Rag2, H. hepaticus infection increased both colon and mammary tumor incidence." (PMID 18941577, 2008). "Six weeks post-injection, tumors developed in all mice (100%, N = 5) with different Rag2 and Il2rγ knockout mutant alleles and a tumor was also noted in the NOD SCID gamma control mouse with a defective immune system which allows proliferation of human mammary carcinoma cells(arrows)." (PMID 29554148, 2018). "We have shown here that Rag2−/−;Il2rg−/− mice allow the metastatic spread of human HER-2+ breast cancer cells, recapitulating the clinical situation." (PMID 22737248, 2012). "STAT1-/- mice developed mammary tumors only, whereas STAT1-/- × RAG2-/- mice developed mammary and intestinal tumors." (PMID 22264274, 2012). "A human breast cancer line MDA-MB-231 stable lines with CtrlKD, CD47KD, ATP6AP2KD, or a double knockdown were established by CRISPR/Cas9 and injected into the mammary fat pad of RAG2-/-, γc-/- mice." (PMID 33603751, 2020). "As an additional control, mammary cancer cell lines established from M/D-driven tumors evolving in Rag2−/− mice always failed to develop tumors when transplanted into WT mice." (PMID 32732875, 2020). "However, since the immunodeficient RAG2-/- mice never developed mammary tumors and the loss of STAT1 expression was observed only in the neoplastic cells of human breast cancers, we hypothesized that STAT1 might act as a cell-intrinsic tumor suppressor in mammary epithelium." (PMID 22264274, 2012). "Mice lacking RAG2 alone did not develop mammary tumors, demonstrating that this phenotype is specifically associated with STAT1 deficiency." (PMID 22264274, 2012). "Mice lacking both Rag2 and Stat1 developed an excess of colon cancer and breast carcinomas." (PMID 29881389, 2018).
leukemia (21 papers, 2011 to 2025). A malignant (clonal) hematologic disorder, involving hematopoietic stem cells and characterized by the presence of primitive or atypical myeloid or lymphoid cells in the bone marrow and the blood. "To validate the xenograft model in oncology research, we injected human-derived leukemia cells (NALM6) intravenously into Il2rg/Rag2 KO rats and analyzed them using IVIS." (PMID 39731164, 2024). "ADAR1 promotes leukemia stem cell (LSC) self-renewal via let-7 pri-microRNA editing ADAR1 knockdown also reduces the self-renewal ability of blast crisis leukemia stem cell (BC-LSC) in RAG2+ γc+ mice." (PMID 37280687, 2023). "We verified that the rag2:Myc + rag2:prl-3 leukemias expressed >10-fold higher levels of PRL-3 than the Myc control group." (PMID 32001668, 2020). "The cross of a Tg(hsp70:Cre) transgenic line with the Tg(rag2:loxP-DsRed-loxP-GFP-Myc) T-ALL model leads to double-transgenics that develop leukemia in 81% of heat shocked larvae." (PMID 32759814, 2020). "The first leukemia model in zebrafish was developed over 15 years ago using the lymphocyte-specific rag2 promoter driving the murine c-Myc oncogene to produce T-cell acute lymphoblastic leukemia (T-ALL)." (PMID 30294597, 2018). "Expression levels of S11 epitope on GFP+ leukemia cells were similar between the wild-type and Rag2-/- recipients (Mean fluorescent intensity (MFI): 3.30 ± 0.19×104 vs. 3.24 ± 0.27×104)." (PMID 27011118, 2016). "We also noted strong inverse correlations between RUNX1 and RAG1/RAG2 mRNA expression in a panel of human leukemias and lymphomas." (PMID 27056890, 2016). "One million MLL/AF9-OVA leukemia cells were transplanted into the wild-type recipients or Rag2-/- recipients, which lack adaptive immune cells (n = 5 for each genotype)." (PMID 27011118, 2016). "When BM cells were analyzed 3 weeks after transfer, the percentages of GFP+ leukemia cells in BM were 0.07 ± 0.07% and 1.22 ± 0.42% in wild-type and Rag2-/- recipients, respectively (p<0.05)." (PMID 26658107, 2015). "NK cell–mediated elimination of leukemia is likely explain why as many as 3 × 104 leukemia cells need to be transplanted to induce leukemia even in Rag2-/- recipients." (PMID 26658107, 2015). "In conclusion, our study demonstrates that BALB/c Rag2-/-γc-/- mice transplanted with human CD34+ cord blood cells provides an in vivo model to define the early steps of HTLV-1 infection that might lead to a better understanding of the initiation of the HTLV-1 associated leukemia." (PMID 21909275, 2011). "Though, the relatively small anti-leukemia efficacy of MI-2 obtained in RAG2-KO mice model may bring to the conclusion that T cells are important component in anti-leukemic MI-2 mechanism of action." (PMID 35296093, 2022). "Importantly, the effectiveness of MI-2 treatment was impaired in TCL1 leukemia-bearing RAG2-KO mice as compared to immunocompetent, wild type mice, suggesting a key role of T cells in the mechanism of action of this drug." (PMID 35296093, 2022). "Whereas wild-type CD4+ T cells control TCL1 leukemia development after adoptive transfer in leukopenic Rag2−/− mice, EOMES-deficient CD4+ T cells failed to do so." (PMID 33526861, 2021). "Gene expression analyses indicated that both the rag2:Myc and rag2:Myc + rag2:prl-3 leukemias expressed the lymphocyte specific genes rag1 and rag2 and the T-cell genes lck and tcrB, but not B-cell related genes igD or igM, indicating all leukemias generated were of T-cell origin." (PMID 32001668, 2020). "In Tg(rag2:jdp2) fish, the kidney marrow was massively infiltrated with blast cells with a monomorphic appearance and high nuclear-to-cytoplasmic ratio, whereas blast cells were readily detectable on peripheral blood smears, indicative of leukemia." (PMID 29941549, 2018).
leukemia (continued). "By contrast, expression levels of R54 and B2 epitope were significantly higher on leukemia cells from wild-type recipients than those from Rag2-/- recipients (R54 MFI: 1.87 ± 0.13×104 vs. 1.29×104 ± 1.69×103, p<0.05; B2 MFI: 8.04 ± 0.78 ×103 vs. 3.45 ± 0.32×103, p<0.05)." (PMID 27011118, 2016). "All Rag2-/- recipients became moribund due to leukemia within 50 days." (PMID 26658107, 2015). "To test whether tumors from Tg(rag2:jdp2) zebrafish harbor leukemia-initiating cells, we exploited a recently developed immune-compromised zebrafish line with a rag2E450fs hypomorphic allele, which is permissive of adoptive transfer of allogeneic zebrafish cells." (PMID 29941549, 2018). "Altogether, these data indicate that the elimination of Tregs from the TCL1 leukemia microenvironment resulted in the expansion of a distinct set of cytotoxic CD8+ T effector cells, capable of clearing leukemia in DEREG and RAG2-KO mice." (PMID 35296093, 2022). "The transgenic Tg(rag2:GFP-Myc) zebrafish line for instance, shows a 100% leukemia incidence with a cancer onset mostly preceding reproductive age." (PMID 32759814, 2020). "Interestingly, the Langenau lab has recently published a brief communication describing a subset of B-cell derived and bi-phenotypic leukemias produced from a rag2 promoter, suggesting some of the research done on these T-ALL models may have unknown contributions from B-ALL as well." (PMID 30294597, 2018). "When the Rag2-/- recipients were analyzed 3 weeks after transfer, the percentages of GFP+ leukemia cells were 1.15 ± 0.04% and 4.85 ± 2.20% in BM and spleen, respectively." (PMID 26658107, 2015). "The injection of 1 × 104 K562-GFP cells reconstituted leukemia in the NSI mice, whereas leukemia cells were under detectable in NOD-scid, IL2Rg−/−, scid, Rag2−/−, nude, or WT mice." (PMID 26022250, 2015). "The non-core domain deletion in both Rag1 and RAG2 led to accelerated leukemia onset and progression, as well as an increased off-target V(D)J recombination." (PMID 39056282, 2024). "In this study, we have demonstrated that non-core region deletion of both Rag1 and Rag2 leads to accelerated development of leukemia and increased off-target V(D)J recombination in mouse models of BCR-ABL1+ B cells." (PMID 39056282, 2024). "The dynamic change of the immunogenicity of MLL-AF9 cells explains why previous studies using similar MLL-fusion leukemia models did not observe the delayed leukemia development in Rag2−/− mice compared to WT mice." (PMID 38129572, 2023). "Consequently, in TCL1-injected RAG2-KO mice, the adoptive transfer of CD8+ T cells isolated from DEREG mice after Tregs depletion, translated into prolonged survival and complete leukemia eradication in three out of nine mice." (PMID 35296093, 2022). "The Rag2: myc-GFP transgene was micro-injected into wild-type zebrafish embryos at the one-cell development stage, and a small fraction of injected embryos developed c-myc induced leukemia." (PMID 31015569, 2019). "Expression levels of H-2Kb and GFP did not significantly differ between the leukemia cells that developed in wild-type recipients and those that developed in Rag2-/- recipients." (PMID 26658107, 2015). "When the minimum numbers of leukemia-initiating cells for engraftment were transferred, leukemia cells were eradicated by the adaptive immune response in most, if not all, wild-type mice, but not in Rag2-/- recipient mice, which lack adaptive immunity." (PMID 26658107, 2015). "We recently reported that MLL-ENL leukemia developed in Rag2-/-γc-/- mice more frequently and rapidly than Rag2-/- mice, suggesting that NK cells can eliminate leukemia cells even in the absence of adaptive immunity." (PMID 26658107, 2015). "In spleen of Rag2-/-, but not wild-type, recipients, distinct leukemia cell population was detected (0.39 ± 0.18%)." (PMID 26658107, 2015).
leukemia (continued). "The data indicate that MLL-AF9 cells cannot grow well in the absence of MHC-I expression in WT and Rag2−/− mice, and it is likely that a small fraction of MLL-AF9 cells that escaped sgRNA-mediated B2m excision expand and predominate over B2m-deficient leukemia cells." (PMID 38129572, 2023). "After the injection of 1 × 105 K562-GFP cells, successful reconstitution of leukemia was observed in NSI (medium survival time 27 days) and NOD-scid (medium survival time 48 days) mice, but not in IL2Rg−/−, scid, Rag2−/−, nude, or WT mice." (PMID 26022250, 2015). "Molecular profiling of isolated leukemia cells confirmed expression of lymphoid (rag1 and rag2) and T-cell specific (lck and tcrβ-C2) markers, with no significant upregulation of B-cell genes (pax5, igD-VH1, and igM-VH1), indicating that PRL-3 did not alter leukemia lineage identity." (PMID 40463094, 2025).